INS (insulin)
Diseases named in the same sentence as INS in open-access papers (continued):
Sharing a sentence is not in itself a finding about the gene and the disease.
Insulin resistance (continued). "Peripheral insulin resistance is also a typical feature of aging, with several studies suggesting that high circulating insulin and insulin resistance to be important contributors to progressive cognitive impairment and neurodegeneration." (PMID 30235271, 2018). "ArKO male mice are obese and develop glucose intolerance and insulin resistance, but supplementation with 17β-estradiol (E2) improves systemic insulin sensitivity." (PMID 30211334, 2018). "A possible role of the brain insulin resistance and a reduced insulin signaling in the AD's pathogenesis, was also described by several studies." (PMID 29479315, 2018). "Insulin resistance is a common pathophysiological condition in which patients present with perturbed biological responses to endogenous insulin leading to compromised glucose homeostasis specifically in liver and skeletal muscle." (PMID 29373583, 2018). "Taking into account the importance of caveolae in insulin signaling, insulin resistance can result, at least partially, from caveolae dysfunction." (PMID 29593789, 2018). "Although phosphorylation of p70S6K is able to contribute to the conduction of insulin signaling, overexpression of p70S6K triggers insulin resistance." (PMID 30420897, 2018). "For instance, low medium pH downregulates the expression of adiponectin, an insulin sensitizer, which modulates chronic inflammation and cell insulin signaling and serves as predictor of insulin-resistance onset." (PMID 29762478, 2018). "Analysis of the insulin signaling pathway revealed that Akt-specific insulin resistance was induced by the HG medium." (PMID 30439990, 2018). "The cross-talk between skeletal muscle and adipose tissue is involved in the development of insulin resistance (IR) in skeletal muscle, leading to the decrease in the anabolic effect of insulin." (PMID 30223577, 2018). "Insulin resistance (IR), wherein cellular responses to insulin are impaired, is a key component of type 2 diabetes and is also implicated in the development of cardiovascular disease." (PMID 29487953, 2018). "During aging, there is an increase of circulating glucose due to the cellular inability to increase glucose uptake in response to insulin, and this peripheral insulin resistance has been related with poorer cognitive function." (PMID 29949869, 2018). "In order to gain insight on the status of insulin resistance in NP-1-treated animals, we also examined the ability of chronic NP-1 administration to modulate insulin-mediated cell signaling in skeletal muscle." (PMID 29959379, 2018). "A large number of recent studies provide compelling evidence that deficits in insulin signaling, arising due to insulin resistance, occurs in AD." (PMID 29950970, 2018). "In N-BMI girls, insulin resistance, plasma insulin and leptin correlated with BMI and body fat % (p < 0.05)." (PMID 29914129, 2018). "To measure insulin resistance, we applied the insulin tolerance test (ITT) at 6 and 11 months of age." (PMID 30079520, 2018). "In human and animal studies, sucrose has been reported to decrease insulin sensitivity and induce insulin resistance, which is a contributing factor to obesity." (PMID 30110343, 2018). "Insulin resistance refers to the impairment of the cellular response in insulin-sensitive tissues such as skeletal muscle, adipose, liver, and brain tissues." (PMID 29643982, 2018). "Inflammation shifts this equilibrium as it induces insulin resistance via cytokines, which alter insulin signaling in endothelial cells, ultimately reducing the production of vasodilating nitric oxide and inducing endothelial dysfunction." (PMID 29675020, 2018). "Palmitate, a typical saturated free fatty acid was used to induce insulin resistance in these cells, thereby reducing insulin signaling." (PMID 28866834, 2018). "Ling reported that BMI and WC were simple predictors of fasting insulin and insulin resistance in overweight and obese adolescents." (PMID 29723977, 2018).
Insulin resistance (continued). "It is important to note, however, that the development of cellular insulin-resistance is often tissue-specific, and several factors associated with systemic insulin resistance may in fact enhance signaling in cells otherwise un-responsive to physiological insulin levels." (PMID 30524379, 2018). "T2DM was characterised by insulin resistance and a higher serum insulin concentration in the HFD- and STZ-induced diabetic mice." (PMID 30337946, 2018). "In our previous study, the elevated plasma glucose levels after an ip glucose load in VLC vs. HC rats, but similar insulin levels, indicated insulin resistance." (PMID 31061673, 2018). "After controlling for body mass index (BMI), WC positively correlated with fasting insulin (r = 0.210, p = 0.007), homeostatic model assessment for insulin resistance (r = 0.249, p = 0.006) and free androgen index (r = 0.249, p = 0.006)." (PMID 30083428, 2018). "The relationship between hypertension and hyperinsulinaemia or insulin resistance is well known, with several studies showing that plasma insulin concentrations increase in obese hypertensives through resistance to insulin-mediated glucose disposal." (PMID 29518898, 2018). "Insulin resistance can be defined as the reduced responsiveness of skeletal muscle, liver, adipose, and vasculature to insulin for the maintenance of nutrient delivery and utilization." (PMID 30018986, 2018). "After 4 weeks on a pecan-rich diet, changes in serum insulin, insulin resistance (HOMA-IR) and beta cell function (HOMA-β) were significantly greater than after the control diet (p < 0.05)." (PMID 29534487, 2018). "The reduced Akt phosphorylation in liver, white adipose tissue, and skeletal muscle in response to insulin stimulation indicates the development of insulin resistance in multiple organs." (PMID 30463387, 2018). "Type 2 diabetes is described as a combination of low amounts of insulin production from pancreatic β-cells and peripheral insulin resistance." (PMID 30545361, 2018). "Pathway-selective hepatic insulin resistance is proposed to explain the failure of insulin to suppress glucose production but support lipogenesis and liver fat accumulation." (PMID 30208938, 2018). "A long prodrome precedes the diagnosis of T2D that includes elevated fasting insulin, obesity, insulin resistance (IR), and dyslipidemia." (PMID 30271382, 2018). "Individuals with insulin resistance lack the ability to fully switch between lipid as a primary fuel source in the fasted state to carbohydrate as a primary fuel source in the insulin-stimulated state." (PMID 30377436, 2018). "Type 2 diabetes (Fig T2D) and obesity are the most frequentendocrine-metabolic diseases that are characterizedby hyperglycemia and impaired insulin action andsecretion (i.e. insulin resistance)." (PMID 29308616, 2018). "In NLRP3 knockout mice, elimination of NLRP3 ameliorated obesity-induced inflammation and insulin resistance, and caspase-1 knockout mice also improved glucose tolerance and insulin sensitivity than wild-type mice after feeding a high-fat diet." (PMID 29497383, 2018). "GLUT4 is also reduced in the adipose tissue in human insulin-resistance and the degree of reduction correlates with whole-body insulin sensitivity." (PMID 30361530, 2018). "Various miRNAs are also involved in the regulation of the main protein cascades of the insulin signaling pathway, thus affecting insulin resistance beyond the development and progression of cancer." (PMID 30453495, 2018). "Nevertheless, these animal models are more expensive, more difficult to breed, kept constant at pathological conditions, and unsuitable for studies of insulin secretagogues because of serious insulin resistance." (PMID 30595798, 2018). "For example, various agents including TNF-α, Interleukin-1 (IL-1), IL-6, free fatty acids, dexamethasone, and high insulin were used to make models of insulin resistance in 3T3-L1 adipocytes." (PMID 30445954, 2018).
Insulin resistance (continued). "Here the authors identify a PKD2 mutation that leads to hyperinsulinemia and insulin resistance in Rhesus monkey and show that PKD2 deficiency promotes beta cell insulin secretion by activating L-type Ca2+ channels." (PMID 29789568, 2018). "The purpose of this study was to improve the HbA1c and BM in obese insulin-resistant T2D patients using the smallest TDD of rapid-acting insulin analog and maximum dose of metformin." (PMID 29215299, 2018). "The HOMA2 model estimates insulin resistance according to fasting glucose concentration and insulin or C-peptide concentrations and takes into account variations in hepatic and peripheral glucose resistance." (PMID 30429669, 2018). "The early stages of the disease are characterized by insulin resistance accompanied by compensatory increases in insulin secretion by pancreatic β-cells for the maintenance of euglycemia." (PMID 29601606, 2018). "Skeletal muscles are the most important insulin-targeted tissue involved in maintaining whole-body glucose homeostasis under insulin-stimulated conditions and are major sites of insulin resistance in T2DM subjects." (PMID 29433422, 2018). "Since insulin resistance is the major driver of MetS, the use of insulin sensitizer is therefore well established, in order to decrease comorbidities that characterize MetS." (PMID 29793496, 2018). "Insulin resistance is a condition in which the response of peripheral tissue to insulin is attenuated and precedes by several years the development of type 2 diabetes mellitus." (PMID 29538286, 2018). "Due to a decline in the secretion of insulin, insulin resistance, and an increase in body mass index (BMI), the prevalence of hyperglycemia and T2D increases with age." (PMID 29857478, 2018). "When fed with a high-fat/high carbohydrates diet, mice homozygous null for the PAI-1 gene display ameliorated insulin and glycemic measures and protective effects against the development of obesity and insulin resistance as compared with wild-type mice." (PMID 29534036, 2018). "Previous studies on insulin-resistance have shown that dysregulation of post-receptor insulin signaling can be influenced by decreased IR tyrosine kinase activity and decreased cell membrane IR expression." (PMID 30453495, 2018). "HT supplementation (10 mg/kg/day for 5 weeks) enhanced glucose tolerance and insulin sensitivity leading to a decrease of homeostatic model assessment-insulin resistance in rat models." (PMID 30002281, 2018). "Elevated TG levels, as well as DG and MG levels, and elevated insulin levels suggest a state of insulin resistance." (PMID 29541056, 2018). "Both the cells and primary neurons demonstrated increased insulin uptake from the surroundings that eventually led to insulin resistance." (PMID 29950970, 2018). "In summary, SIRT2 deletion in vivo reduces muscle insulin sensitivity and contributes to liver insulin resistance by a mechanism that is unrelated to cytosolic acetylation state." (PMID 30533032, 2018). "Reactive oxygen species (ROS), FFA and pro-inflammatory cytokines (e.g. IL-6) have been shown to inhibit insulin signaling and contribute to insulin resistance." (PMID 29444133, 2018). "For this reason, it is still of enormous importance to study the role of IL-13 in the pathogenesis of insulin resistance, also evaluating the possible existence of a state of IL-13 action resistance in patients with altered insulin sensitivity." (PMID 29675435, 2018). "Adipose tissue is an insulin-sensitive organ that plays an important role in oxidative stress and subsequently on insulin resistance." (PMID 31565649, 2018). "Lect2 deletion attenuates muscle insulin resistance in dietary obese mice, and Lect2 transfection in myocytes decreases insulin signaling." (PMID 29630667, 2018). "Metformin, a drug that targets protein kinase activity and which is widely used for the treatment of insulin resistance, is believed to operate mainly by activating the insulin signaling pathway AMPK." (PMID 30093963, 2018).
Insulin resistance (continued). "Mouse models show that the pituitary is still sensitive to changes in insulin levels despite peripheral insulin resistance and basal hyperinsulinemia." (PMID 29743077, 2018). "Other findings showed thatexenatide lowered glucose, insulin, and insulin resistance, which was consistentwith a previous study of GLP-1 analogs in patients of type 2 diabetes." (PMID 29924135, 2018). "A sedentary lifestyle contributes to insulin resistance, while increased physical activity improves insulin sensitivity and whole-body glucose and lipid metabolism." (PMID 30250846, 2018). "T2DM is a metabolism correlation disease; its main symptoms are hyperglycemia, insulin resistance, and decrease of insulin secretion." (PMID 30544624, 2018). "The disease develops insidiously through periods of increased insulin secretion, insulin resistance, impaired glucose tolerance, and β-cell dysfunction." (PMID 29487749, 2018). "After PD, insulin resistance (IR), as measured by insulin, HOMA-IR and QUICKI, improved significantly, although C-peptide and HOMA-β decreased." (PMID 29718860, 2018). "In the condition of insulin resistance, how do these epigenetic modification enzymes influence each other and consequently act on insulin sensitivity?" (PMID 30574122, 2018). "Lipid intermediates produced during triacylglycerols (TAGs) synthesis and lipolysis in adipocytes interfere with the intracellular insulin signaling pathway and development of insulin resistance." (PMID 29940972, 2018). "In cellular assays, they protected pancreatic β cell from oxidative damage, increased insulin release, improved insulin resistance, displayed α-glucosidase inhibition activity, and suppressed liver gluconeogenesis." (PMID 29983732, 2018). "Impaired glucose transport by a defect in insulin-mediated Glut-4 translocation induces insulin resistance." (PMID 30116491, 2018). "Although these mice developed insulin resistance, glycaemia is normal due to increased insulin levels." (PMID 29449530, 2018). "Mice were placed on a chow or Western diet (WD) to induce insulin resistance over 12 weeks; they were then subjected to insulin tolerance testing (ITT)." (PMID 30135298, 2018). "The increased insulin resistance in mother sows also results in elevated insulin-mediated glucose and free fatty acid levels, allowing for greater substrate availability for newborn piglets growth." (PMID 30197635, 2018). "T2DM is characterized by a dysfunctional carbohydrate, lipid and protein metabolism resulting from a progressively impaired insulin secretion and/or insulin resistance." (PMID 30563087, 2018). "Both disorders are characterized by peripheral insulin resistance combined with a relative insufficiency in pancreatic beta-cell insulin production." (PMID 30513672, 2018). "Hyperinsulinemia further increases insulin resistance by damaging insulin receptor at cell site including pancreatic beta cells and responsible for reduction in insulin secretion in later stage of type 2 diabetes." (PMID 30072892, 2018). "This defect was observed in a range of in vitro insulin resistance models and adipose tissue from insulin-resistant humans and was concomitant with lower expression of mevalonate/CoQ biosynthesis pathway proteins in most models." (PMID 29402381, 2018). "In agreement, overexpression of Mfn2 improved diet-induced hepatic insulin resistance and chemical chaperones ameliorated glucose tolerance and insulin signalling in liver-specific Mfn2 KO mice." (PMID 29538286, 2018). "Our results suggest that insulin resistance measured by GU is partially similar in all insulin-sensitive tissues, skeletal muscle, adipose tissue and liver and are affected by obesity, aging and gender." (PMID 29535167, 2018). "In patients with MS and insulin resistance, the later applies only to the metabolic effects of insulin, whereas the mitogenic action is maintained and even exaggerated by the associated hyperinsulinemia." (PMID 29495350, 2018).
Insulin resistance (continued). "In order to further confirm pinocembrin's influence on the alleviation of insulin resistance, the phosphorylation of key Akt/mTOR signaling proteins was assayed in insulin-resistant HepG2 cells after pinocembrin treatment." (PMID 30420897, 2018). "According to the classical view, obesity-induced insulin resistance is primary, and rise in insulin levels is a compensatory response to insulin resistance, mediated by raised levels of glucose." (PMID 30307959, 2018). "Insulin resistance, the primary abnormality of and risk factor for T2DM, is characterized by reduced insulin-mediated glucose uptake in skeletal muscle, liver and adipose tissue in people with normal glucose tolerance." (PMID 30149556, 2018). "Note, SOCS2 deletion was shown to protect against hepatic steatosis but worsens insulin resistance in high-fat-diet-fed mice while ablation of SOCS3 enhances hepatic insulin sensitivity but increases lipogenesis resulting in fatty liver and obesity." (PMID 30547786, 2018). "In this study, insulin resistance was observed with reduction of glycogen content and a reduction in insulin signaling activities." (PMID 30374328, 2018). "Their proposed anti-diabetic activity is reportedly due to their ability to attenuate insulin resistance and improve insulin secretion, with evidence to support these claims found in various clinical trials." (PMID 29601521, 2018). "As the skeletal muscle is the primary tissue for glucose uptake and therefore plays a critical role in the pathogenesis of insulin resistance, we analyzed correlations between skeletal muscle lipids and insulin sensitivity measured through the Matsuda ISI." (PMID 30322152, 2018). "TLR4 is abundantly expressed in insulin target tissues such as adipose tissue, liver and skeletal muscle and is now accepted as a key player in obesity-induced insulin resistance and T2DM." (PMID 29666152, 2018). "Intriguingly, Gdf15−/− mice fed AMLN diet for 30 weeks also had increased fasting glucose/insulin levels and homeostatic model assessment of insulin resistance (HOMA-IR) index compared to control mice." (PMID 29717162, 2018). "In another study, performed in five patients with acromegaly and insulin-resistance, treatment with pegvisomant for 12 weeks improved metabolic parameters, reducing significantly fasting insulin level, FGP and HbA1c." (PMID 30034367, 2018). "We are proposing, as surrogates of insulin resistance, cut-off points for post-stimulus insulin and glucose concentrations in a pediatric population." (PMID 29082896, 2018). "The genetics of fetal insulin release and/or action have been suggested to affect fetal growth, adult insulin resistance and adult body composition." (PMID 30514227, 2018). "T2D manifests as insulin resistance whereby utilization of endogenously produced insulin is altered at the target cells." (PMID 29621153, 2018). "During a state of insulin resistance, cells exhibit decreased sensitivity to stimulation by insulin, which presents as a reduction in the tyrosine phosphorylation levels of IRβ and IRS and results in insufficient uptake of glucose and amino acids." (PMID 29973864, 2018). "Insulin resistance is a lessened capability of insulin to properly activate the insulin signaling pathway that is responsible for the stimulation of glucose uptake and metabolism." (PMID 29513799, 2018). "Along with hyperglycemia, insulin resistance, fully abolished insulin secretion and β-cell apoptosis, tissues were more inflamed in old HFD mice than in young, including a more and stronger pro-inflammatory and reduced anti-inflammatory cytokine expression." (PMID 29426925, 2018). "Pharmacologic or genetic manipulations that decreased mitochondrial CoQ triggered mitochondrial oxidants and insulin resistance while CoQ supplementation in either insulin-resistant cell models or mice restored normal insulin sensitivity." (PMID 29402381, 2018).